POMC (proopiomelanocortin)
Diseases named in the same sentence as POMC in open-access papers (continued):
Sharing a sentence is not in itself a finding about the gene and the disease.
Sepsis (continued). "In contrast, proopiomelanocortin (POMC)-specific PC1/3 knockout mice phenocopied global PC1/3 knockout mice, including an enlarged spleen size and a hyperinflammatory sepsis phenotype in response to mild endotoxemia." (PMID 39435302, 2024). "The findings of these studies are compatible with glucocorticoid-receptor-ligand-binding-induced inhibition of pituitary processing of POMC into ACTH and with preserved CRH/AVP-driven expression of POMC, resulting in elevated circulating POMC levels in sepsis." (PMID 33593393, 2021). "To test this hypothesis, we first documented plasma concentrations of POMC in relation to ACTH and cortisol in acute and prolonged human critical illness evoked by sepsis." (PMID 33593393, 2021). "Furthermore, the knocking down experiment by a central lentiviral approach indicated that hypothalamic POMC expression contributed to the enhancement of hepatic GNG in sepsis rats, but was not required for the anti‐inflammatory action of insulin." (PMID 29285858, 2018). "Therefore, the liver protective and anti‐inflammatory effect of insulin in sepsis rats could be independent of hypothalamic POMC." (PMID 29285858, 2018). "More interestingly, we found that POMC knockdown had no significant impact on the activities of hepatic enzyme markers (ALT and AST) and NF‐κB pathway with or without insulin treatment in sepsis rats." (PMID 29285858, 2018).
hypocortisolism (55 papers, 2007 to 2026). "ACTH is synthesized in anterior pituitary corticotropes upon processing of its precursor, proopiomelanocortin (POMC) and indeed POMC null mice or patients carrying a mutation in the POMC gene have severe hypocortisolism." (PMID 29536250, 2018).
pheochromocytoma (53 papers, 2006 to 2026). "However, in case of ACTH-secreting pheochromocytoma, a paradoxical increase in ACTH levels post-glucocorticoid administration was observed, which was found to be mediated by demethylation of the E2F-binding site in the POMC promoter." (PMID 33266265, 2020).
small cell lung carcinoma (43 papers, 2007 to 2025). Small cell lung cancer (SCLC) is a highly aggressive malignant neoplasm, accounting for 10-15% of lung cancer cases, characterized byrapid growth, and early metastasis. "E2F1 corticotroph specificity also seems to be subclass specific: E2F1 but not E2F3 enhanced POMC promoter activities by deletion mutant hPOMC luciferase assays using ectopic ACTH-secreting tumor cells derived from human small cell lung cancer DMS79 cells." (PMID 30147673, 2018).
epilepsy (41 papers, 2012 to 2026). A brain disorder characterized by episodes of abnormally increased neuronal discharge resulting in transient episodes of sensory or motor neurological dysfunction, or psychic dysfunction. "POMC was also found to be co-expressed with SCN4B in our analysis, and it has been previously associated to epilepsy." (PMID 32331418, 2020).
glucocorticoid deficiency (41 papers, 2009 to 2026). "A few years ago, we reported glucocorticoid deficiency in two unrelated patients with apparent ACTH resistance due to an unusual mutation in POMC: the p.R8C mutation in the sequence encoding ACTH and α-MSH." (PMID 28228747, 2017).
type 2 diabetes (39 papers, 2013 to 2025). "Glucose sensing by POMC neurons became defective in obese mice fed a HFD, suggesting that loss of glucose sensing has a causal role in the development of type 2 diabetes." (PMID 25759638, 2015).
carcinoid tumor (36 papers, 1988 to 2025). A slow growing neuroendocrine tumor, composed of uniform, round, or polygonal cells having monotonous, centrally located nuclei and small nucleoli, infrequent mitoses, and no necrosis. "(E) Schematic of sensor and signal genes expressed by a ‘composite’ carcinoid tumor cell (T) from data in D. Genes shown are those expressed in>15% of the profiled tumor cells, plus POMC (14% of tumor cells), INHBB (14%), and OPNSW1 (6%)." (PMID 36469459, 2022). "Similarly, silent POMC expression has been observed in carcinoid tumors without EAS." (PMID 38035072, 2023).
Glucose intolerance (36 papers, 2007 to 2025). Glucose intolerance (GI) can be defined as dysglycemia that comprises both prediabetes and diabetes. "Maternal obesity also causes lifelong weight gain and glucose intolerance associated with a disruption in POMC and AgRP axonal projections during adulthood." (PMID 41223213, 2025). "Interestingly, loss of BBS1 in POMC neurons led to glucose intolerance and insulin insensitivity, whereas BBS3 deficiency in these neurons is associated with slight impairment in glucose handling, but normal insulin sensitivity." (PMID 38223458, 2024). "Knockdown of CaSR in adult mice specifically in the hypothalamic arcuate nucleus, where GHRH, POMC and AgRP neurons reside, also resulted in increased body weight, adiposity, leptin resistance, and glucose intolerance, and reduced bone mass." (PMID 40501942, 2025). "Congruently, the implantation of hypothalamic stem cells with impaired IKK/NF-κB signaling in HFD-fed mice increases neurogenesis and POMC neuronal differentiation, and reduces body weight, food intake, glucose intolerance and insulin levels." (PMID 35112705, 2022). "Knockout of HIF2α specifically in hypothalamic POMC-producing neurons reduced the insulin-induced increase in POMC gene expression and led to aging-related hyperphagia, weight gain, and glucose intolerance." (PMID 33917812, 2021). "In the previous studies, the inhibition of autophagy by depleting autophagy genes in POMC neurons inhibits POMC axonal innervation and increases fat mass and glucose intolerance in later life." (PMID 33188191, 2020). "Our findings are generally consistent with previous studies demonstrating that maternal obesity causes lifelong weight gain and glucose intolerance associated with disruption in AgRP/NPY and POMC axonal projections during adulthood." (PMID 32163401, 2020). "For instance, defective autophagy in POMC neurons leads to glucose intolerance and obesity, whereas disrupted autophagy in glucose-sensing AgRP neurons promotes leanness and reduces food intake." (PMID 30700738, 2019). "To further confirm that hypothalamic POMC prevents glucose intolerance, we restored eutopic POMC expression by crossing arcPomc−/− mice with a tamoxifen inducible Cre mouse line." (PMID 30283405, 2018). "In addition, conditional loss of the calcitonin receptor (Calcr) in proopiomelanocortin (POMC) neurons of the hypothalamus leads to increased body weight gain, increased adiposity, and glucose intolerance as a result of microglial IL-6 release." (PMID 36890585, 2023). "Consistently, mice with ablated POMC neurons develop glucose intolerance." (PMID 36210455, 2022). "In addition, selective loss of autophagy (i.e., loss of Atg7) in POMC neurons decreased α-melanocyte-stimulating hormone levels (an active derivative of POMC), increased body weight, and raised adiposity and glucose intolerance likely controlling energy balance." (PMID 28593174, 2017). "The interruption of insulin or glucose signaling in POMC neurons leads to glucose intolerance without changing energy homeostasis." (PMID 30283405, 2018). "In summary, we show for the first time a protective role of hypothalamic POMC peptide against glucose intolerance by mechanisms that are independent of POMC role in energy balance." (PMID 30283405, 2018). "Altogether, these results suggest that POMC prevents glucose intolerance by improving insulin sensitivity through mechanisms not related to energy balance regulation or fat storage." (PMID 30283405, 2018). "We found that JNK3 deficiency in POMC neurons of HFD-fed mice caused no significant changes in feeding behavior, glucose intolerance, blood glucose concentration, hypertrophy of white and brown adipocytes, and hepatic steatosis compared with control Pomc-cre (PomcWT) mice." (PMID 26910012, 2016).
hypothyroidism (36 papers, 2011 to 2026). Abnormally low levels of thyroid hormone. "Single-cell sequencing of ARC neurons revealed that Thra and Thrb are expressed in AgRP and POMC neurons, and that their expression levels are similar in both physiological states, suggesting that hypothyroidism in IBA animals is not caused by receptor downregulation." (PMID 38987241, 2024).
hyperandrogenism (30 papers, 2009 to 2026). Excessive secretion of androgens from the adrenal glands or gonads. "Intriguingly, hyperandrogenism has not been reported in POMC-deficient mammals, further suggesting the presence of distinct mechanisms of leptin-POMC signaling and adrenal steroid synthesis in teleosts and mammals." (PMID 35937837, 2022).
metabolic syndrome (30 papers, 2010 to 2026). A cluster of metabolic risk factors for CARDIOVASCULAR DISEASES and TYPE 2 DIABETES MELLITUS. "Higher pro-opiomelanocortin (POMC) methylation in cord blood was associated with hyperinsulinemia in children blood, suggesting an early predictive marker of future metabolic syndrome." (PMID 31849831, 2019). "POMC neurons are critical components of the network regulating energy balance in mammals and loss of POMC neurons is associated with development of metabolic syndrome." (PMID 25358444, 2014). "α-MSH is one cleavage product of the pituitary hormone pro-opiomelanocortin (POMC), and numerous studies have described the role of POMC in metabolic syndrome." (PMID 37275985, 2023). "As one of POMC’s downstream effector hormones, decreased α-MSH may be a potential risk factor for metabolic syndrome in several mental illnesses." (PMID 37275985, 2023). "Studies of POMC neurogenesis may therefore lead to the identification of molecular mechanisms that help to prevent metabolic syndrome." (PMID 36033614, 2022). "If stored cord blood was available, the methylation levels of proopiomelanocortin (POMC), the melanocortin 4 receptor (MC4R), and hepatocyte nuclear factor 4 alpha (HNF4a; associated with metabolic syndrome) were assayed in participants in check-up examinations at the ages of 7-9 years." (PMID 33677859, 2021). "Higher methylation and lower expression of proopiomelanocortin (POMC) in cord blood was associated with lower birth weight and higher triglycerides in children blood, suggesting an early predictive marker of future metabolic syndrome." (PMID 31849831, 2019).
Hyperinsulinemia (24 papers, 2012 to 2025). An increased concentration of insulin in the blood. "Higher pro-opiomelanocortin (POMC) methylation level in umbilical cord blood is associated with hyperinsulinemia in children, which may serve as a marker for future MetS." (PMID 40568560, 2025). "At weaning, SL offspring exhibit hypermethylation of the hypothalamic POMC promoter, which seems to be involved in the impairment of POMC expression even in the presence of hyperinsulinemia." (PMID 35631188, 2022). "Targeting FA synthesis in POMC neurons may help prevent hyperinsulinemia and fat accumulation." (PMID 40541585, 2025).
Bardet-Biedl syndrome (23 papers, 2019 to 2025). A ciliopathy with multisystem involvement. "Similar clinical features are also observed in patients suffering from HO syndrome due to a genetic abnormality (i.e. melanocortin-4 receptor defect, leptin or proopiomelanocortin (POMC) deficiency, Bardet-Biedl Syndrome)." (PMID 37780616, 2023). "However, the current weight-loss strategies do not effectively treat genetic-related diseases, such as generalized lipodystrophy, Bardet-Biedl syndrome, and proopiomelanocortin (POMC) deficiency." (PMID 37937009, 2023). "Rare MC4R pathway diseases of obesity include proopiomelanocortin, proprotein convertase subtilisin/kexin type 1, or leptin receptor deficiency, or Bardet-Biedl syndrome (BBS)." (PMID 40847358, 2025). "For example, setmelanotide, a MC4R agonist is FDA approved for treatment of monogenic obesity related to POMC deficiency, leptin receptor (LEPR) deficiency, and Bardet Biedl syndrome." (PMID 37780616, 2023). "Although multiple melanocortin receptor agonists have been investigated, setmelanotide is currently the only MC4R agonist approved by the FDA for the treatment of specific genetic forms of obesity, including deficiencies in POMC, PCSK1, and LepR, as well as Bardet-Biedl syndrome (BBS)." (PMID 41016636, 2025). "Congenital disorder of HO mainly includes abnormalities in the leptin‐melanocortin pathway, leading to monogenic obesity syndrome, such as Prada–Willi syndrome (PWS), melanocortin‐4 receptor (MC4R) defect, leptin or proopiomelanocortin (POMC) deficiency, and Bardet–Biedl syndrome." (PMID 39661011, 2025). "POMC, PCSK1, and LEPR deficiencies and Bardet-Biedl syndrome (BBS) can be counter-regulated by the MC4R agonist setmelanotide." (PMID 40822950, 2025). "Informed by these mechanistic studies, successful phase 3 clinical trials have led to a second generation MC4R agonist being licensed in many countries for the treatment of several monogenic disorders (POMC, PCSK1, LEPR deficiencies and Bardet-Biedl Syndrome (BBS))." (PMID 37661743, 2023). "Approved from age 2, but limited to specific genetic disorders (e.g., biallelic POMC, LEPR, Bardet-Biedl syndrome), and may be used in this age range (genotype-restricted)." (PMID 41212412, 2025).
hypogonadotropic hypogonadism (21 papers, 2013 to 2025). Abnormal ovarian or testicular function due to insufficient hormonal stimulation from the hypothalamic-pituitary axis. "These phenotypic features are different from those of global Kiss1r-KO mice, which suffer from severe central hypogonadism, or mice with conditional inactivation of Kiss1r in GnRH neurons, which phenocopy global Kissr1-KO mice, or in POMC neurons, which are devoid of a detectable phenotype." (PMID 38861336, 2024).
mood disorder (20 papers, 2017 to 2025). A cognitive disorder a disturbance in which the person's mood is hypothesized to be the main underlying feature. "It is therefore possible that an interaction of BDNF, CREB1, GNAS, and POMC genes with exposure to chronic stress or traumatic life events increase the risk of cardiometabolic and mood disorders either simultaneously, or through mediating factors." (PMID 28117839, 2017). "Recent studies have identified genetic variants linked to both mood disorders and cardiometabolic conditions, including CACNA1D, FTO, BDNF, POMC, IGF." (PMID 39834212, 2025). "POMC is also one of the shared genes between mood disorder and cardiometabolic diseases." (PMID 33815158, 2021). "Amongst hypothalamic neurons, proopiomelanocortin (POMC) neurons in the arcuate nucleus of the hypothalamus (ARC) play a critical role in controlling energy balance and mood disorders." (PMID 41321745, 2025). "The INF contains two distinct populations of neurons, the pro-opiomelanocortin (POMC)-expressing neurons and the neuropeptide Y (NPY)-expressing neurons, that are both involved in mood disorders (MD) and suicide." (PMID 38263257, 2024). "An elevation of the number of pro-opiomelanocortin+ (POMC, an endogenous opioid precursor) neurons in the INF, which was due to a high proportion of POMC+ neurons that co-expressed PR, was related to suicide in patients with mood disorders (MD)." (PMID 38263257, 2024).
autism (17 papers, 2007 to 2024). Persistent deficits in social interaction and communication and interaction as well as a markedly restricted repertoire of activity and interest as well as repetitive patterns of behavior. "Together, p38α in POMC and AgRP neurons play distinct roles in regulating autism-like behaviors." (PMID 38570876, 2024). "We found that POMC was correlated with autism, which was consistent with previous study." (PMID 32093803, 2020).
-dependent (16 papers, 2009 to 2026). "Collapse association of POMC rare variants with substance dependence (SD) or body mass index (BMI)." (PMID 23028917, 2012).
Stroke (15 papers, 2011 to 2025). Sudden impairment of blood flow to a part of the brain due to occlusion or rupture of an artery to the brain. "The pituitary POMC gene levels were also increased in ND/veh mice at 3 days post-stroke, but the levels were still lower than those in DD/STZ mice." (PMID 35784349, 2022). "The POMC gene expression was further increased in DD/STZ mice at 1 day post-stroke while the levels in ND/veh mice remained similar to the levels in pre-ischemia and sustained until 3 days post-stroke." (PMID 35784349, 2022). "We also confirmed increased levels of hypothalamic CRH, pituitary POMC, and plasma corticosterone in diabetic mice before and after stroke, suggesting the hyper-activated HPA axis in diabetic conditions." (PMID 35784349, 2022). "In the current study, we found the overall increased hypothalamic CRH, pituitary POMC, and plasma corticosterone levels in both normal and diabetic mice after stroke." (PMID 35784349, 2022). "In the pituitary gland, we found significantly elevated mRNA levels of POMC (the precursor of ACTH) in the anterior pituitary in DD/STZ mice compared to ND/veh before stroke." (PMID 35784349, 2022). "Despite the upregulated POMC in the pituitary, plasma ACTH levels were not significantly higher in DD/STZ mice before and after stroke." (PMID 35784349, 2022).
autoimmune adrenalitis (14 papers, 2013 to 2026). "In the Tpit knock-out mouse model, inactivation of the Tpit gene results in loss of POMC expression in corticotropes and adrenal hypoplasia." (PMID 34564059, 2021).
lung carcinoma (14 papers, 1982 to 2025). "Moreover, POMC-negative expression was associated with better response to paclitaxel and carboplatin chemotherapy in lung cancer." (PMID 40823088, 2025).
Arthritis (13 papers, 2009 to 2022). Inflammation of a joint. "We conducted ISH to investigate activation of the HPA axis caused by acute mono-arthritis based on gene expression levels of HPA axis-related peptides including AVP hnRNA and CRH mRNA in the pPVN and POMC mRNA in the AP." (PMID 32117068, 2020). "It is important to note that food restriction resulted in decreased values of both POMC and CART mRNA expressions compared to the other dietary regimes with or without arthritis." (PMID 20953376, 2010). "In addition, food-restriction led to a more profound decrease of mRNA expressions for anorexigenic factors (POMC, CART, IL-1β) and marked increase of mRNA expressions for orexigenic factors (NPY, AgRP) compared to the other dietary regimes with or without arthritis." (PMID 20953376, 2010). "These experiments demonstrate a lack of synergy between prednisolone and dipyridamole on POMC expression or ACTH secretion in corticotroph cells, unlike the synergistic anti-inflammatory activity of the combination observed in human PBMCs, mouse macrophages, and in rat arthritis models." (PMID 19171052, 2009).
anxiety disorder (12 papers, 2009 to 2024). A category of psychiatric disorders which are characterized by anxious feelings or fear often accompanied by physical symptoms associated with anxiety. "In panic and anxiety disorder, miR-488 has been shown to regulate proopiomelanocortin, a precursor to the HPA hormone, adrenocorticotropin." (PMID 31740756, 2020).
craniopharyngioma (11 papers, 2010 to 2025). A benign, partly cystic, epithelial tumor of the sellar region, presumably derived from Rathke pouch epithelium. "Damage to the hypothalamus from craniopharyngiomas and other tumours will result in disruption of POMC activation of PVH magnocellular oxytocin neurons and the release of oxytocin via α-melanocyte stimulating hormone and will thus abrogate the anorexigenic effect of oxytocin." (PMID 35464063, 2022).